CIDEA (cell death inducing DFFA like effector a)
Description:
Lipid transferase that promotes unilocular lipid droplet formation by mediating lipid droplet fusion. Lipid droplet fusion promotes their enlargement, restricting lipolysis and favoring lipid storage. Localizes on the lipid droplet surface, at focal contact sites between lipid droplets, and mediates atypical lipid droplet fusion by promoting directional net neutral lipid transfer from the smaller to larger lipid droplets (By similarity). The transfer direction may be driven by the internal pressure difference between the contacting lipid droplet pair and occurs at a lower rate than that promoted by CIDEC (By similarity). May also act as a CEBPB coactivator in epithelial cells to control the expression of a subset of CEBPB downstream target genes, including ID2, IGF1, PRLR, SOCS1, SOCS3, XDH, but not casein (By similarity). By interacting with CEBPB, strengthens the association of CEBPB with the XDH promoter, increases histone acetylation and dissociates HDAC1 from the promoter (By similarity). When overexpressed, induces apoptosis; the physiological significance of its role in apoptosis is unclear (By similarity).
Synonyms: CIDE-A
Tractability: No criterion of Open Targets' tractability assessment is met for any kind of drug.
Gene: Protein-coding gene on chromosome 18 (12,254,361 to 12,277,595, forward strand). Ensembl gene ENSG00000176194.
Subcellular location: Lipid droplet; Nucleus
Pathways (Reactome):
Developmental Biology: Transcriptional regulation of brown and beige adipocyte differentiation by EBF2
Metabolism: Lipid particle organization
Gene Ontology:
Molecular function: lipid transfer activity; phosphatidic acid binding; transcription coactivator activity; protein homodimerization activity
Biological process: lipid droplet fusion; lipid storage; negative regulation of cytokine production; negative regulation of lipid catabolic process; negative regulation of tumor necrosis factor production; apoptotic process; fat cell differentiation; lipid metabolic process; negative regulation of cold-induced thermogenesis; negative regulation of execution phase of apoptosis; negative regulation of transforming growth factor beta receptor signaling pathway; positive regulation of cold-induced thermogenesis; regulation of apoptotic DNA fragmentation; temperature homeostasis; cellular response to cold; intermembrane lipid transfer; negative regulation of multicellular organismal process; positive regulation of DNA-templated transcription; response to stilbenoid
Cellular component: lipid droplet; cytoplasm; cytosol; mitochondrial envelope; mitochondrion; nucleus
Genetic constraint (gnomAD): Loss-of-function variants: 10 observed, 16.51 expected, observed/expected ratio (o/e) 0.61, 90% interval 0.37 to 1.03. The upper end of that interval is the gene's LOEUF score, 1.03, which puts it in group 4 of 6, group 1 being the genes least tolerant of losing a copy. Missense variants: 309 observed, 303.21 expected, observed/expected ratio (o/e) 1.02, 90% interval 0.93 to 1.12. Synonymous variants: 128 observed, 129.59 expected, observed/expected ratio (o/e) 0.99, 90% interval 0.86 to 1.14.
Homologues: Orthologues: chimpanzee CIDEA (95% identical), macaque CIDEA (95% identical), mouse Cidea (83% identical), rabbit CIDEA (81% identical), pig CIDEA (78% identical), rat Cidea (78% identical), dog CIDEA (78% identical), guinea pig CIDEA (76% identical), tropical clawed frog cidea (53% identical), zebrafish cidea (44% identical), Drosophila melanogaster Drep2 (26% identical). Paralogues in human: CIDEC (44% identical), CIDEB (40% identical), DFFA (23% identical).
Diseases named in the same sentence as CIDEA in open-access papers:
CIDEA is named in the same sentence as 41 diseases in open-access papers, as found by Europe PMC text mining. Sharing a sentence is not in itself a finding about the gene and the disease. The quoted sentences say what the papers report.
Obesity (20 papers, 2007 to 2025). Accumulation of substantial excess body fat. "In white adipose tissues from patients with obesity and insulin resistance, CIDEA expression is linked to high triglyceride accumulation." (PMID 40862768, 2025). "Expression of this gene, which has been associated with lipolysis and obesity with CIDEA-null mice being resistant to diet-induced obesity, was downregulated in Mal animals." (PMID 36118759, 2022). "Steatosis and/or obesity were thus associated with the upregulation of the hepatic expression of CIDEA, FSP27α and β." (PMID 31097771, 2019). "CIDEA‐deficient mice are resistant to obesity and show higher metabolic rates in BAT." (PMID 33598207, 2021). "CIDEA polymorphism has also been associated with obesity in human, although this could be more closely related to its role in adipose tissue." (PMID 31097771, 2019). "New interventions targeting LEP, NOTCH1, SPRY1, PPARG, ID2, and CIDEA gene network, in addition to what already is going on, can be designed for treatment and prevention of both obesity and tumors." (PMID 35395810, 2022). "As previously demonstrated, the hepatic expression of CIDEA is increased in a mouse model of diet-induced obesity and hepatic steatosis." (PMID 31097771, 2019). "Interestingly, the expression of CIDEA, which was found downregulated in VAT and main predictor of NAFLD, has been positively associated with human obesity but inversely related to NAFLD severity." (PMID 34638880, 2021). "Overall, a number of interesting genes that could play a role in obesity susceptibility have been identified within these CNVs (e.g. ASTN2, APOA2, PARK2, LINGO2, PLCB1, PTEN, and CIDEA)." (PMID 29441128, 2018). "We also sought to determine if the AGE/RAGE/DIAPH1 axis is linked to markers of adipogenesis (PPARG & PPARGC1A) and metabolic genes that we previously identified to be regulated by RAGE in a mouse model of obesity (UCP1 and CIDEA)." (PMID 34103691, 2021). "We first evaluated the hepatic expression levels of CIDEA, CIDEB and FSP27α and β in dietary mouse models of obesity and hepatic steatosis." (PMID 31097771, 2019). "We here report that the hepatic expression of CIDEA and FSP27 (α/β) was similarly upregulated in a dietary mouse model of obesity-mediated hepatic steatosis." (PMID 31097771, 2019). "Among genes that may regulate basal lipolysis and indirectly, insulin action in fat cells, only CIDEA, PDE3B and receptors for testosterone displayed different expression in men with obesity (higher values) compared with women with obesity." (PMID 38491191, 2024). "CIDEA is involved in apoptosis, while mice lacking functional CIDEA are resistant to obesity and diabetes; CIDEA mRNA is expressed in the white human fat cells and in brown mouse adipocytes, and low adipose CIDEA expression is associated with metabolic syndrome." (PMID 35630580, 2022).
Hepatic steatosis (11 papers, 2007 to 2026). Steatosis is a term used to denote lipid accumulation within hepatocytes. "Mechanistically, cell death-inducing DFF45-like effector family members A (CIDEA) was identified as a downstream mediator of METTL16-driven hepatic steatosis." (PMID 41952207, 2026). "ACC, FASN, PPARG, CIDEC, and especially CIDEA are all involved in the onset of hepatic steatosis and lipid droplet fusion in MASLD." (PMID 39958875, 2024). "Thus, one mechanism by which KPA ameliorates hepatic steatosis is by negatively regulating CIDEA expression." (PMID 40862768, 2025). "CIDEA is a key gene regulating AKT-induced hepatic steatosis." (PMID 39958875, 2024). "The role of CIDEA in hepatic triglyceride accumulation and lipid droplet formation has been clearly demonstrated and its targeting (overexpression and down regulation) regulates hepatic steatosis in obese mice." (PMID 31097771, 2019). "CIDEA is a PPAR-gamma target, and its deficiency alleviates the hepatic steatosis caused by HFD30." (PMID 28827783, 2017). "Interestingly, our findings indicated a marked increase in both mRNA and protein levels of CIDEA following AKT overexpression and the onset of hepatic steatosis." (PMID 39958875, 2024). "Hepatic expression of CIDEA, FSP27 α and β also correlated with hepatic steatosis and liver injury." (PMID 31097771, 2019). "Moreover, supplementation was able to downregulate genes, such as CIDEA (cell death-inducing DFFA-like effector A) and Apoa4 (apolipoprotein A-IV), which are known to be related to hepatic steatosis and inflammation." (PMID 28587078, 2017).
breast tumor (5 papers, 2010 to 2024). "Among them, CIDEA (Cell Death-Inducing DFFA-Like Effector A) is downregulated in breast tumors, suggesting its significant role in lipid metabolism and energy balance with implications for cancer cell survival and proliferation." (PMID 38253993, 2024). "This is in agreement with the previous findings that AQP7 expression was down-regulated in breast tumor and CIDEA and CIDEC are cell death-inducing DFFA-like effectors to activate apoptosis." (PMID 26618778, 2015). "For example, we found that the gene cell death-inducing DFFA-like effector a (CIDEA) exhibited hypermethylation in promoter CpG islands (CGIs) and decreased expression in breast tumor samples relative to normal tissues (LIMMA; fold change = 0.03; FDR = 7.51e−199)." (PMID 35739271, 2022). "In our research, expression of marker genes of fat browning, like UCP1, PRDM16, CIDEA, COX7A1, PGC1α, TMEM26 and TBX1, was up-regulated in adipose tissue adjacent to breast tumors." (PMID 25291184, 2014).
Insulin resistance (5 papers, 2007 to 2025). Increased resistance towards insulin, that is, diminished effectiveness of insulin in reducing blood glucose levels. "It is known to mediate lipolysis and insulin resistance by downregulation of PLIN1 and CIDEA expression." (PMID 27900559, 2017). "CCDC3 alleviates glucose intolerance, insulin resistance and steatosis formation in transgenic CCDC3 mice on high-fat diet (HFD) by reducing the expression of hepatic PPARγ and its target gene CIDEA as well as other genes involved in de novo lipogenesis." (PMID 28827783, 2017). "Overall, CIDEA was up-regulated in adipose tissue of individuals with successful long term insulin resistance relapse and not in adipose tissue of unsuccessful individuals." (PMID 24983748, 2014).
diabetes (3 papers, 2007 to 2022). "Since CIDEA-null mice have been reported to have a lean phenotype and resistance to diabetes, class III lines may represent definitive BA progenitors with certain advantages over fetal or adult-derived BAT cells for potential use in transplantation therapy." (PMID 30616682, 2019).
steatosis (3 papers, 2007 to 2019). Increased lipid within the cytoplasm of cells. "Although the underlying mechanism(s) remains to be elucidated, we found that the significant decrease of PPAR-gamma and CIDEA mRNA levels in the livers of CCDC3 TG mice compared to that in control mice must account for the this anti-steatosis phenotype." (PMID 28827783, 2017). "To address the human relevance of our findings, we examined the relationship between hepatic CIDEA, CIDEB, CIDEC1 and CIDEC2 expression and the NAFLD progression from normal liver to steatosis and subsequent NASH in human liver biopsies from morbidly obese patients seeking for bariatric surgery." (PMID 31097771, 2019).
colorectal tumors (2 papers, 2010 to 2024). "Studies have shown that compared with normal colonic mucosa, the expression of brown fat-associated protein (CIDEA) in colorectal tumors increased significantly." (PMID 39099656, 2024).
glioma (2 papers, 2015 to 2020). A benign or malignant brain and spinal cord tumor that arises from glial cells (astrocytes, oligodendrocytes, ependymal cells). "Taken together, our findings indicate that CIDEA regulates several pathways associated with glioma cell survival." (PMID 27551468, 2015). "In glioblastoma, CIDEA is reportedly down-regulated and is a regulator of glioma cells, where ectopic expression of CIDEA triggered apoptosis, actin cytoskeletal disruption, and cell cycle arrest." (PMID 33614508, 2020). "As reciprocal relation exists between PPAR and HIF-1α: and as HIF-1α is a key component in glioma progression, their role in regulating CIDEA expression in glioblastoma was investigated." (PMID 27551468, 2015). "This study highlights for the first time the existence of (i) PPARγ-CIDEA regulatory loop in glioma and (ii) novel function of CIDEA as regulator of glioma cell survival." (PMID 27551468, 2015). "Taken together, this study not only suggests the existence of a CIDEA-PPARγ regulatory loop, but also demonstrates the role of CIDEA as death inducer in glioma cells." (PMID 27551468, 2015). "To study the mechanistic detail of PPARγ mediated transcriptional regulation of CIDEA in glioma cell, we chose a 1120 bp genomic region (−1000 to +120) on the CIDEA promoter." (PMID 27551468, 2015). "Thus, CIDEA negatively regulates HIF-1α activation in glioma cells." (PMID 27551468, 2015).
adrenal tumors (1 paper, 2022). "They assessed in the perirenal region of PPGL higher expression of UCP1, CIDEA, ELOVL3, EBF3, FBXO31 and LHX8, but not TNFSRF9, TBX1 or TMEM26, in comparison with seven subjects with non-functional adrenal tumors." (PMID 35327387, 2022).
fibrosis (1 paper, 2019). the formation of excess fibrous connective tissue in an organ or tissue in a reparative or reactive process. "Since CIDEA expression is mainly dependent on SREBP1c9,10 and the down-regulation of SREBP-1c has been associated with the development of burned-out NASH34, the decrease in CIDEA could reflect the severity of NAFLD (NASH with fibrosis)." (PMID 31097771, 2019).
glioblastoma (1 paper, 2020). The most malignant astrocytic tumor (WHO grade IV). "Aside from ESCC, public database results also showed that CIDEA was down-regulated in other malignant tumor types such as bladder urothelial carcinoma (BLCA), breast invasive carcinoma (BRCA), glioblastoma multiforme (GBM), head and neck squamous cell carcinoma (HNSC)." (PMID 33614508, 2020).
hepatocellular carcinoma (1 paper, 2024). A malignant tumor that arises from hepatocytes. "Our findings from the in vitro model further indicated that CIDEA overexpression in hepatocellular carcinoma cells led to a notable increase in LD size, whereas the application of HLSP resulted in a significant reduction in LD dimensions." (PMID 39958875, 2024). "We transfected the CIDEA plasmid in HepG2 and Huh-7 hepatocellular carcinoma cells, respectively, and both observed significantly high expression of CIDEA at the protein level." (PMID 39958875, 2024). "Similarly, we achieved comparable outcomes by overexpressing CIDEA in HepG2 and Huh-7 hepatocellular carcinoma cells." (PMID 39958875, 2024).
lymph node metastasis (1 paper, 2020). "CIDEA down regulation was significantly correlated with poor tumor differentiation, advanced clinical staging, and lymph node metastasis." (PMID 33614508, 2020).
cancer (10 papers, 2015 to 2025). A tumor composed of atypical neoplastic, often pleomorphic cells that invade other tissues. "The CpG site cg20950011 influences the methylation of the CIDEA gene, which is involved in adipose tissue loss in cancer cachexia." (PMID 40177272, 2025). "The CIDEA protein has been shown to play a role in lipolysis in animal models and humans, and has also been suggested to play a role in human cancer cachexia." (PMID 37345090, 2023). "CIDEA expression was particularly increased in the adipocytes of cachectic cancer patients likely due to their reduced body size and low adiposity, determined by the presence of a poor nutrition status." (PMID 35454855, 2022). "The brown fat-like phenotype characterized by CIDEA expression may be due to the infinite plasticity of cancer stem cells, which can differentiate into multiple cell lines with various phenotypes according to gene mutations and microenvironment factors." (PMID 39099656, 2024). "Cell death-inducing DNA fragmentation factor-alpha-like effector A (CIDEA) and Peroxisome proliferator-activated receptor gamma coactivator-1-α (PGC-1α) have been shown to be involved in regulating wasting and browning of adipose tissues in cancer cachexia." (PMID 36428623, 2022).
tumor (7 papers, 2010 to 2024). "Additionally, we also found that the down-regulation of CIDEA in ESCC was positively associated with tumor differentiation, TNM stage, lymph node metastasis." (PMID 33614508, 2020). "However, mRNA expression of CIDEA, a lipid droplet-associated protein, was 2-fold higher in tumour-bearing animals compared to the reference animals." (PMID 29258509, 2017). "Therefore, there should be some other factors to facilitate the tumor suppressor function of CIDEA, which required further experiments to elucidate." (PMID 33614508, 2020). "The protein expression of CIDEA was determined by Western blotting analysis in 10 pairs of ESCC and non-tumor tissues and via IHC in a tissue microarray (TMA) containing 248 pairs of ESCC and non-tumor tissues." (PMID 33614508, 2020). "In summary, we report that CIDEA was frequently downregulated in ESCC and functions as a tumor-suppressor by regulating ESCC proliferation and apoptosis through the JNK-p21/Bad pathway." (PMID 33614508, 2020). "The down-regulation of CIDEA was detected in all the 78 ESCC tissues, but only observed in 46/78 (58.9%) of non-tumor tissues." (PMID 33614508, 2020). "Elevated CIDEA expression and diminished PRKACA, which phosphorylates and activates HSL, suggests that lipolysis was inhibited in tumour-bearing animals." (PMID 29258509, 2017). "Of these up-regulated genes, the greatest impact was on the expression of CIDEA (14.0-fold increase, p<0.0067), GML (26.4-fold increase, p<0.0004), and IP6K3 (18.1-fold increase, p<0.0001) in the LS-174T tumor xenografts." (PMID 25268703, 2014).
metabolic disease (2 papers, 2014 to 2020). A congenital disorder (due to inherited enzyme abnormality) or acquired (due to failure of a metabolically important organ) disorder resulting from an abnormal metabolic process. "Originally described as involved in apoptosis, CIDEA plays important roles in the development of metabolic disorders and lipid metabolism." (PMID 24983748, 2014).
CIDEA also shares sentences with these, for which no sentence is quoted: metabolic syndrome (3 papers); Cachexia (2); esophageal squamous cell carcinoma (2); Hyperinsulinemia (2); acute lymphocytic leukemia (1); autism (1); bladder cancer (1); breast carcinoma (1); chronic kidney disease (1); Cohen syndrome (1); Glucose intolerance (1); head and neck squamous cell carcinoma (1); Infertility (1); leukaemia (1); lung carcinoma (1); Macrocephaly (1); myelolipomas (1); non-alcoholic fatty liver disease (1); oral cancer (1); Pigmentary retinopathy (1); prostate tumour (1); schizophrenia (1); Simpson-Golabi-Behmel syndrome (1); Truncal obesity (1); type 2 diabetes (1).